BRCA1 (BRCA1 DNA repair associated)
Diseases named in the same sentence as BRCA1 in open-access papers (continued):
Sharing a sentence is not in itself a finding about the gene and the disease.
breast cancer (continued). "In this study, we analyze the functional impact of PAF-AH on BRCA1 mutant breast cancer and explore its relationship to the Wnt signaling pathway." (PMID 36614323, 2023). "EZH2 directly interacts with other proteins such as breast cancer gene 1 (BRCA1) binding to EZH2 in breast cancer cells." (PMID 37325482, 2023). "Breast cancer genes 1 and 2 (BRCA1 and BRCA2) are important players in mammary tumor development in both humans and canines." (PMID 37835752, 2023). "BRCA1 and BRCA2 (heretofore BRCA) germline pathogenic variant (PVs) carriers are at a significantly higher risk for breast cancer (BC), with estimated cumulative lifetime risk of 55% to 65% and 45% to 47%, respectively." (PMID 37370730, 2023). "Hereditary pathogenic/likely-pathogenic variants (PVs/LPVs) of BRCA1 and BRCA2 genes are the principal genetic cause of breast cancer (BC), ovarian cancer (OC), and other malignancies such as prostate (PrC) and pancreas (PC) carcinomas." (PMID 37046793, 2023). "The impact of contralateral RRM on prognosis in BRCA1/2 breast cancer patients depends on the stage of detected BC (secondary contralateral BC vs. generalization of primary BC)." (PMID 36831416, 2023). "Analyzing the 29 BRCA1-methylation-positive breast cancer patients separately revealed similar results to those of the overall group of BC patients, where the expression of miR-155-5p was significantly higher in patients compared to controls (p = 0.004)." (PMID 37240365, 2023). "Unnafected female carriers of BRCA1 and BRCA2 pathogenic/likely pathogenic variants (P/LPVs) are at higher risk of breast cancer (BC) and ovarian cancer (OC)." (PMID 36831416, 2023). "When it comes to breast cancer genomics, two of the most important genes that can possibly increase the lifetime risk of hereditary breast and ovarian cancer in general, and early-onset breast cancer in specific, are the BRCA1/2 genes." (PMID 36685821, 2022). "Previous study have demonstrated that reduction of BRCA1 in breast cancer cell can increase the sensitivity of cisplatin and also lead to the resistance of anti-microtubule drugs (such as paclitaxel and vincristine)." (PMID 36193432, 2022). "Especially mutations in BRCA1/FANCS and BRCA2/FANCD1 caused ovarian cancer and breast cancer in women." (PMID 36685883, 2022). "A 61-year-old female (BRCA1 carrier) with a family history of BRCA1 breast cancer (mother and grandmother) underwent bilateral preventive (prophylactic) mastectomy in March 2010." (PMID 35200583, 2022). "In contrast, in other systems, it has been shown that PARP inhibitors, together with IR, have very good effects such as in BRCA1(+/−) lymphoblastoid cells, hepatocellular cancer and lung and breast cancer xenografts." (PMID 36612094, 2022). "For instance, the upregulation of UHRF1 in breast cancer was shown to result in hypermethylation and inhibition of BRCA1 by forming an inhibitory transcriptional complex consisting of HDAC, DNMT1, and G9a over its promotor." (PMID 36077796, 2022). "Basic studies have reported that VEGF3 inhibitors can elevate the chemical sensitization of ovarian cancer stem cells by downregulating BRCA1/2, but the specific mechanism in breast cancer still needs further exploration with basic experiments." (PMID 36077621, 2022). "Thus, Brca1 deficiency may result in the ATP11blo and Ptdss2hi phenotype that facilitates externalization of PS, which may account for the higher rate of metastasis of Brca1-MT mammary tumors." (PMID 35025764, 2022).
breast cancer (continued). "It is well known that BRCA1/2, the vital DNA repair genes, play a particularly important role in cancer in women, such as breast cancer and ovarian cancer." (PMID 35205332, 2022). "SMAD4 mRNA levels correlate with the expression of some DDR genes, pointing to a possible signature role for SMAD4 similar to BRCA1 in breast cancer." (PMID 35144669, 2022). "Here, we performed a systematic multiomics analysis to expound BRCA1/2 functions as prognostic biomarkers in breast cancer." (PMID 35409110, 2022). "Cancer is a disease of the genome, therefore, its development has a clear Mendelian component, demonstrated by well-studied genes such as BRCA1 and BRCA2 in breast cancer risk." (PMID 35459932, 2022). "BRCA1 and BRCA2 are tumour suppressor genes that are strongly associated with the early development of breast cancers in both, men, and women, but with distinct differences." (PMID 35804947, 2022). "In a previous review of the literature, we found that 50% of overall BRCA1/2 breast cancer cases are missed when genetic testing criteria are used." (PMID 35805038, 2022). "In this manuscript we describe a method of detecting BRCA1-type HRD in breast cancer (BC) solely from RNA sequencing data by identifying TDs surfacing in transcribed genes." (PMID 35159019, 2022). "Breast cancer 1 (BRCA1) and breast cancer 2 (BRCA2) play an important role in the HR repair pathway by interacting with other DNA repair proteins such as Fanconi anemia (FA) proteins, ATM, RAD51, PALB2, MRE11A, RAD50, and NBN." (PMID 35785170, 2022). "al reported the fraction of BRCA1/2 biallelic alterations as 94.0% and 84.7% in TCGA ovarian and breast cancer cohorts, respectively." (PMID 35578198, 2022). "Two breast cancer women that are double heterozygotes (DH) for both BRCA1/BRCA2, one ovarian cancer case DH for BRCA1/RAD51C, and another breast and colorectal cancer who is DH for BRCA2/PMS2 were identified in our cohort." (PMID 36232793, 2022). "Breast cancer proteins, especially BRCA1 and BRCA2, participate in homologous recombination repair (HRR)." (PMID 35963853, 2022). "A clinical study using PARP inhibitors, such as Olaparib and BSI-201, is now ongoing and shows clinical efficacy in the treatment of BRCA1/2-related breast, ovarian, and prostate cancers, as well as sporadic basal-like breast cancers." (PMID 35744786, 2022). "Polyamine accumulation has previously been correlated with the increased proliferation of both hormone-dependent and independent breast cancer cells, and was recently found to contribute to BRCA1-mediated DNA repair." (PMID 35954325, 2022). "In PDX models of BRCA1-deficient breast cancer, responses of the BRCA1-methylated PDX tumours to alkylating agents and Olaparib were comparable with those of the BRCA1-mutated model." (PMID 35681784, 2022). "We also demonstrate a co‐dependency of TSG101 and BRCA1/2 for the survival of breast cancer cells, similar to the synthetic lethality observed for PARP inhibitor olaparib and BRCA1/2 deficiency." (PMID 36124865, 2022). "Very often, EZH2 is associated with the aberrant expression of proteins with a major role in a given cancer, as, for example, BRCA1 in ovarian and breast cancers." (PMID 36230683, 2022). "Significantly increased Ezh2 expression in female BRCA1-deficient K14cre; Brca1F/F; Trp53F/F (KB1P) mouse mammary tumors compared to BRCA1-proficient K14cre; Trp53F/F (KP) mammary tumors was further corroborated by RNA sequencing of tumor tissue (p = 0.0156)." (PMID 35715861, 2022). "For example, BRCA1 and BRCA2, two major genes mapped to the long arms of chromosomes 17 and 13, determine predisposition to breast cancer." (PMID 34981672, 2022). "Breast cancer genes 1 and 2 (BRCA1/2) act as tumour suppressors, assisting in preventing tumorous growths." (PMID 35933387, 2022).
breast cancer (continued). "Oral poly (ADP-ribose) polymerase inhibitor olaparib in patients with BRCA1 or BRCA2 mutations and advanced breast cancer: a proof-of-concept trial." (PMID 36197199, 2022). "The current study has convincingly shown that PVs in BRCA1 are the biggest contributor to breast cancer in women diagnosed aged ≤30 years." (PMID 33758026, 2022). "Between July 2018 and September 2021, 105 breast cancer patients underwent BRCA1/2 genetic testing in our department." (PMID 35191009, 2022). "BRCA1 is also known to be inactivated in sporadic breast cancer by somatic promoter hypermethylation, suggesting that both the germline and somatic inactivation of these genes play a critical role in BC tumorigenesis." (PMID 35806485, 2022). "Since poly ADP-ribose polymerase (PARP) is also essential in DNA repair, PARP inhibitors (PARPis) cause synthetic lethality in tumors with BRCA1 and/or BRCA2 germline mutations and are used for ovarian, prostate, pancreatic, and breast cancer." (PMID 36371386, 2022). "BRCA1 and BRCA2 mutation carriers have a very high risk of breast cancer and ovarian cancer by age 70, at 47–66% and 40–57%, respectively, and of other malignancies, including PC." (PMID 35761384, 2022). "The FA pathway has been associated with PARP inhibitor resistance in head and neck cancers, and the overexpression of FANCD2 confers PARP inhibitor resistance in BRCA1/2 mutant breast cancer cells." (PMID 35999268, 2022). "Most recently, olaparib was further approved for adjuvant treatment of patients with BRCA1/2-mutated, high-risk HER2-negative early breast cancer." (PMID 36284291, 2022). "Cultural social roles associated with gender and communication processes are linked to the equation that BRCA1 and BRCA2 are «genes responsible for breast cancer» (and “only women have breasts”)." (PMID 35303741, 2022). "In addition, polygenic risk scores (PRS) of common variants, developed for association with first breast cancer, have been shown to predict CBC in the general BC population and in BRCA1/2 mutation carriers, particularly the extensively validated 313 SNP PRS." (PMID 36271417, 2022). "In one couple with a family history of breast cancer undergoing PGT for monogenic diseases, we confirmed a previously identified pathogenic BRCA1 variant in the mother." (PMID 35314819, 2022). "BRCA1 and BRCA2 are associated with the DNA repair pathway and together, are the most common genetic cause for breast cancer, accounting for approximately 5% of all cases." (PMID 35813042, 2022). "ART558 is a small-molecule Polθ inhibitor that has a synergistic effect with PARPi, and it has a stronger inhibitory effect on cells (including ovarian cancer and breast cancer cells) when used at the same time in BRCA1/2 mutant cells." (PMID 36091750, 2022). "In this cross-sectional population-based study of 8,162 breast cancer patients, 323 (4.0%) had germline BRCA1 or BRCA2 PVs." (PMID 35143328, 2022). "In these cancers, the BRCA1 gene acts as a tumor suppressor to repress the expansion of basal stem cells and basal-like breast cancers." (PMID 36207293, 2022). "Although the function of the BRCA1 gene has been extensively studied, the relationship between BRCA1 gene expression and tumor aggressiveness remains controversial in sporadic breast cancers." (PMID 34996912, 2022).
breast cancer (continued). "In an observational cohort study of MRI in combination with mammography among unaffected female BRCA1/2 heterozygotes, the probability of dying of breast cancer within 20 years was 2%." (PMID 36353115, 2022). "PARP inhibition has been shown to be a promising therapeutic strategy in homologous recombination repair-deficient tumors, such as BRCA1 and BRCA2-mutated breast cancer." (PMID 36139701, 2022). "Patients with hereditary mutations in BRCA1 or BRCA2 (gBRCA1/2) and breast cancer have distinct tumor biology, and encompass a predilection for brain metastasis (BM)." (PMID 35393462, 2022). "BRCA1 (breast cancer gene 1) is a nuclear phospholipid, which inhibits breast cancer and ovarian cancer tumors." (PMID 35310909, 2022). "Together, these results reveal VNGD as a potential therapeutic target acting in concert with DNA damaging therapeutics including conferring PARPi‐sensitivity to WT BRCA1 breast cancer cells." (PMID 36047643, 2022). "Findings also indicated that NOTCH1 promotes EMT, leading to TNBC formation in BRCA1-defective conditions, correlating with human BRCA1-mutant breast cancer samples showing high levels of mesenchymal markers." (PMID 36497409, 2022). "To our knowledge, this is the first and largest WGS study of BRCA1/2 modifiers to date, and we report PPARGC1A as a novel putative genetic modifier of ovarian and breast cancer risk for BRCA1/2 carriers." (PMID 35625955, 2022). "This is of high clinical significance because clinical trials have previously shown that a small proportion of BRCA-1 wild-type breast cancer patients can benefit from platinum-based therapies." (PMID 35626009, 2022). "This implies that despite the low total heritability explained by polymorphisms in these genes, monitoring genetic variations in BRCA1 and BRCA2 is advantageous for the diagnosis of breast cancer in high-risk patients." (PMID 35743744, 2022). "The BRCA1/2 mRNA level in breast cancer tissues was considerably higher than in normal tissues, with AUCs of 0.766 and 0.829, respectively." (PMID 35409110, 2022). "Knock-in or knock-out mice can be generated that either promote the expression of various oncogenes such as HRAS in breast cancer, or silence the effect of tumour-suppressor genes such as Brca1 in breast cancer, respectively." (PMID 36295541, 2022). "In breast cancer cells, E3 ligase BRCA1 and CUEDC2 have been shown to regulate PGR protein stability." (PMID 35244538, 2022). "Evaluation of BRCA1/2 molecular status has become the standard of care in the treatment of individuals with breast cancer." (PMID 36140751, 2022). "A few genes including BRCA1, BRCA2, and ATM have been known to be associated with the risk of breast cancer." (PMID 36268271, 2022). "For example, mutations in BRCA1 and BRCA2 increase the risk of breast cancer, and mutations in RAD51 increase the risk of rectal cancer." (PMID 35991565, 2022). "Breast cancer mean onset was 4.6 years earlier in BRCA1 carriers compared to BRCA2 (p = 0.07, a trend) and ovarian cancer onset almost 11 years earlier in BRCA1 families (p < 0.05)." (PMID 35469032, 2022). "Breast cancer type 1 susceptibility protein (BRCA1), a DNA repair protein typically associated with breast cancer, is hypomethylated in AD." (PMID 35575089, 2022).
breast cancer (continued). "Two high-penetrance genes (BRCA1 and BRCA2) are responsible for about 16% of the familial risk of breast cancers and associated with a 60–80% lifetime risk of developing breast cancer." (PMID 34128142, 2022). "In this study, 454 carriers of mutations in the BRCA1 gene and 273 carriers of mutations in the BRCA2 gene were included under 50 years of age, and 261 had a personal history of breast cancer." (PMID 35805026, 2022). "Women who carry pathogenic variants in BRCA1 (OMIM 113705) and BRCA2 (OMIM 600185) have greatly increased risk of developing breast cancer." (PMID 36203093, 2022). "Significantly more breast cancer with ki67 > 30%, EGFR-positive breast cancer, and CK5/6-positive breast cancers were also seen in BRCA1 mutation carriers." (PMID 35209950, 2022). "Our study showed that it is mandatory to consider the complex interplay between the type of BRCA1 and BRCA2 pathogenic variants, age at primary breast cancer diagnosis, breast cancer subtype and stage, and systemic treatment received." (PMID 36580360, 2022). "We performed a meataanalysis of BRCA1 or BRCA2 germline pathogenic or likely pathogenic variant (gBRCA) in 108,699 unselected breast cancer patients and in 238,972 unaffected individuals." (PMID 35805038, 2022). "At present, no personalized guidelines are available for the prophylactic management of second primary breast cancer in patients with the BRCA1 and BRCA2 pathogenic variants with unilateral breast cancer who underwent BCT as a primary procedure." (PMID 36580360, 2022). "The functional role of estrogen in breast cancer etiology and the potential integrative role between BRCA1 and the hormone synthesis are under-investigated in BRCA1." (PMID 34643844, 2022). "Among all the different molecular subtypes of breast cancers, only luminal A and B subtypes were selected to compare BRCA1 mRNA levels because both subtypes are ER+." (PMID 34996912, 2022). "The repetitive elements are abundant in the 28-gene panel which contains most of the breast cancer-related genes, for instance, the BRCA1 gene has around 40% of Alu family repetitive elements in its DNA sequences." (PMID 35493102, 2022). "In the present study, we show that HspBP1 has anti-tumorigenic effects in breast cancer in a BRCA1-dependent manner." (PMID 35387978, 2022). "There were 25 breast cancer patients with pathogenic variants, 6 with likely pathogenic variants, and 65 with VUS in the BRCA1 gene." (PMID 35918668, 2022). "Surprisingly, hypoxia preferentially blocked HDAC inhibitor-induced differentiation of BRCA1-reconstituted breast cancer cells." (PMID 36612206, 2022). "A similar finding was observed in another Brca1-MT mammary tumor cell line, 628, which was derived from a Brca1-MSK mouse with multiorgan metastasis." (PMID 35025764, 2022). "Women with pathogenic variants in high penetrance genes such as BRCA1 and BRCA2 have a 40-80% lifetime risk of breast cancer compared to 12% risk in the general population." (PMID 36387260, 2022). "There was a negligible increase in survival for carriers of the pathogenic variants BRCA1 and BRCA2 with TN breast cancer and who received any secondary prevention strategy compared with surveillance." (PMID 36580360, 2022). "The two familial breast cancer (BC) genes, Breast Cancer gene 1 (BRCA1) and Breast Cancer gene 2 (BRCA2), are highly penetrant and contribute to various cellular events ranging from the response to DNA damage to control of the cell cycle and apoptosis." (PMID 35464868, 2022). "This study also showed the BRCA1-dependent antiproliferative action of 1,25(OH)2D in breast cancer cell lines." (PMID 35328609, 2022).